NOTCH3 (notch receptor 3)
Diseases named in the same sentence as NOTCH3 in open-access papers (continued):
Sharing a sentence is not in itself a finding about the gene and the disease.
lung carcinoma (continued). "Preliminary results indicated that the differences in Notch3 expression in lung adenocarcinoma were the most prominent and, accordingly, those specimens were collected from adult thoracic (lung) cancer surgerical resections." (PMID 23420695, 2013). "Our results showed that the reduction of Notch3 expression induced the increase of cell apoptosis in all three lung cancer cell lines." (PMID 24367688, 2013). "In contrast, one study has proven that overexpression of Notch3 promots the growth of human lung cancer cells in vitro and inhibits the differentiation of lung cancer cells in transgenic mice." (PMID 23599800, 2013). "The results revealed that among the three groups of specimens of lung cancer, the expression of Notch3 was the highest in squamous cell carcinoma and adenocarcinoma, and was the lowest in SCLC." (PMID 23420695, 2013). "Notch3 affects apoptosis and tumor growth in lung cancer by co-operating with the EGFR-MAPK pathway." (PMID 23426998, 2013). "The expression of Notch3 in lung cancer tissues was detected by reverse transcription polymerase chain reaction (RT-PCR) and western blot analysis to further explore the role of Notch3 in adult lung adenocarcinoma." (PMID 23420695, 2013). "Bruceine H, a derivative of Brucea javanica (L.), was found to overcome resistance to receptor tyrosine kinase (RTK)‐EGFRi in non‐small cell lung cancer (NSCLC) models by suppressing Notch3, EGFR activation and β‐catenin expression., thereby increasing gefitinib response." (PMID 37697969, 2023). "This includes accumulating evidence that alteration of NOTCH3 signalling plays an important role in the development and pathogenesis of chronic obstructive pulmonary disease, lung cancer, asthma, idiopathic pulmonary fibrosis and pulmonary arterial hypertension." (PMID 36052538, 2022). "Therefore, the remainder of this review will summarise recent new findings from ours and other groups, which highlight the pathogenic role of NOTCH3 in mediating severe respiratory diseases such as COPD, viral infections, lung cancer, asthma, IPF and PAH." (PMID 36052538, 2022). "Based on our study results, we concluded that BH substantially suppressed Notch3 signaling in human lung cancer, resulting in powerful antitumor activity in human lung cancer both in vitro and in vivo, and that it can improve the sensitivity of resistant NSCLC to gefitinib." (PMID 35463301, 2022). "In contrast to Notch1 and Notch3, which are regarded as oncogenic factors responsible for lung cancer development, whether Notch2 has similar roles should be further investigated." (PMID 34485133, 2021). "NOTCH3 signaling plays different roles in lung cancer cell lines." (PMID 29765324, 2018). "Moreover, high Notch3 expression in lung cancer represented a higher possibility of being resistant to chemotherapy." (PMID 25996086, 2015). "Notch3 may be involved in the pathogenesis of bronchogenic carcinoma, in particular in the promotion of the lung cancer oncogene, and a difference in its expression may exist in the various pathological types." (PMID 23420695, 2013). "Therefore, we speculated that if TANs promoted the migration and invasion of lung cancer via Notch3." (PMID 35118116, 2021). "Thus, NOTCH3 is an important therapeutic target in lung cancer." (PMID 29765324, 2018). "Moreover, chemotherapy targeting NOTCH3 should be able to assault lung cancer on multiple fronts." (PMID 29765324, 2018). "High Notch3 expression may contribute the resistance to chemotherapy in lung cancer patients." (PMID 28061457, 2017). "Finally, the effect of Notch3 in lung carcinoma has been observed to be strongly dependent on cell type being a tumor suppressor in Small Cell Lung Cancer (SCLC) and a tumor promoting in NSCLC by differentially modulating cell adhesion, Epithelial Mesenchymal Transition (EMT), and cell motility." (PMID 27847554, 2016).
lung carcinoma (continued). "In lung cancer, EVO suppresses tumor growth and metastasis, potentially by inhibiting the Notch homolog 3 (NOTCH3) signaling pathway." (PMID 41226811, 2025). "PNO1/CRISPR/Cas9 inhibited the expression of Notch1, Notch2, Notch3 Jagged1, and DLL1 in lung cancer A549 and H460 cells." (PMID 36625087, 2023). "In lung cancer, MFNG suppresses Notch3 activation, subsequently inhibiting tumor growth in vitro and in vivo." (PMID 35804829, 2022). "To verify the roles of Notch3 in tumorigenesis and the relationship of Notch3 with GPX4 and PRDX6, we established an in vivo xenograft model using Notch3 knockdown lung cancer cells." (PMID 35258176, 2022). "With a relatively loose threshold (p < .2), the genes Dhx16, Upf2, Denr, Notch3, Dyrk2, Sec61a1, Hmmr, and Noa1 were reversed in at least three treatment protocols and most of these genes were reported to be related to COPD or lung cancer." (PMID 35993327, 2022). "In addition, Li, Zhang have suggested that CHIR99021 up-regulated the Notch3 protein expression and its downstream genes and accelerated cell proliferation in human lung cancer cells, although the regulation of CHIR99021 on apoptosis might vary depending on the cell type." (PMID 36496849, 2022). "PKCί knockdown led to reduced levels of ELF3 and stem-like phenotypes in lung cancer cells, including A549 and H358 cells, and decreased ELF3 binding to the promoter region of NOTCH3." (PMID 34830169, 2021). "Studies suggest that NOTCH3 is mainly expressed in NSCLC, and has been proposed as a therapeutic target of lung cancer." (PMID 29765324, 2018). "Glycine decarboxylase (GLDC), PKCι, Notch3, and integrin β3-KRAS-RalB have been shown to play important roles in the acquisition and maintenance of stemness in lung cancer." (PMID 25965829, 2015). "Another study showed that while inhibition of EGFR led to significant cell death in EGFR-mutant lung cancer cells, it increased stemness properties, e.g., higher ALDH+ population and increased clonogenicity, which was likely driven by an increase in Notch 3 expression." (PMID 32575680, 2020). "Furthermore, it has been also demonstrated that Notch3 inhibition abrogated the colony and tumor-forming ability of ALDH-positive cells in lung cancer." (PMID 30723507, 2019). "Here, we evaluated the in vivo and in vitro anti-lung cancer effects of EVO, and examined whether NOTCH3 signaling is involved in the EVO’s anti-cancer action." (PMID 29765324, 2018). "Previous studies suggested that selective Notch3 inhibition (rather than pan-Notch inhibition) combined with EGFR TKI therapy should be explored as a novel strategy in the treatment of lung cancer patients." (PMID 29795369, 2018). "To determine whether the induction of Notch3 and β-catenin signaling is observed in human EGFR mutant NSCLC, we evaluated Notch3 and β-catenin levels in human lung cancer biopsies before and after erlotinib therapy." (PMID 30097569, 2018). "We have observed this ectopic expression in human lung cancer samples regardless of the expression of Notch3 in the cancer cells." (PMID 28719575, 2017). "Immunohistochemistry and imaging analysis were used to detect the expression of Notch3 in lung cancer and negative tissue margins." (PMID 23420695, 2013). "However, in contrast to the role that has been described for stromal Notch3 in lung cancer, we observed here that stromal Notch3 had no impact on patient’s survival." (PMID 36854682, 2023). "Our research here shows that bruceine H suppressed the proliferation, migration, and invasion of lung cancer cells; inhibited the growth of human NSCLC cell xenografts; and enhanced the therapeutic effects of gefitinib in the PC-9/GR xenograft models, possibly by inhibiting Notch3." (PMID 35463301, 2022).
lung carcinoma (continued). "In summary, there is rapidly accumulating evidence that alteration of NOTCH3 signalling in the adult human lung plays an important role in the development and pathogenesis of multiple acute and chronic lung diseases, including COPD, viral infections, lung cancer, asthma, IPF and PAH." (PMID 36052538, 2022). "In this study, we used 5-aza as a positive control, and found that combination with 5-aza diminished EVO’s anti-lung cancer effects and the inhibition of NOTCH3 activation, suggesting that EVO may inhibit NOTCH3 signaling by activation of the DNMTs-induced NOTCH3 methylation." (PMID 29765324, 2018).
cerebral small vessel disease (50 papers, 2015 to 2026). Cerebral small vessel disease is the term currently used to pathological processes that affect the brain parenchymal circulation (arterioles, capillaries, and veins). "This clinical evidence suggests that NOTCH3 mutations cause more than cerebral small-vessel disease and have an important association with intracranial large-artery stenosis, although most cases have been described only in East Asia." (PMID 41018180, 2025). "In the past, it was thought that NOTCH3 mutations caused pure cerebral small-vessel disease-classical CADASIL." (PMID 41018180, 2025). "It is a rare hereditary cerebral small vessel disease, attributed to mutations in the NOTCH3 gene located on chromosome 19." (PMID 38489688, 2024). "Cerebral autosomal dominant arteriopathy with subcortical infarcts and leucoencephalopathy, caused by cysteine-altering variants in NOTCH3, is the most prevalent inherited cerebral small vessel disease." (PMID 38162905, 2024). "Extensive genetic analysis of NOTCH3 in inherited cerebral small vessel disease has identified hundreds of pathogenic mutations as well as variants of uncertain significance." (PMID 37209821, 2023). "Second, we excluded concurrence of other mutation in NOTCH3 and common causative genes related to cerebral small-vessel disease or vascular dementia." (PMID 34335700, 2021). "Genetic variants in NOTCH3 gene have been shown to be associated with cerebral small vessel disease, while NOTCH4 variants linked to Alzheimer's disease." (PMID 34257585, 2021). "Looking from the other side, nonsense NOTCH3 mutation or constitutive activation of NOTCH3 signaling can be related to the pathogenesis of different cerebral small vessel disease from CADASIL." (PMID 32457593, 2020). "Genetic variants of Notch3 and Notch4 genes are associated with cerebral small vessel disease 27 and Alzheimer's Disease 28, respectively." (PMID 28568708, 2017). "More studies are needed in the future to demonstrate whether CADASIL can be expanded from classical cerebral small vessel disease to a new spectrum of diseases that share the same pathogenesis as mutations in the NOTCH3 gene." (PMID 41018180, 2025). "This suggests that NOTCH3 mutations cause more than just classical cerebral small-vessel disease and may involve large intracranial arteries and extracranial diseases." (PMID 41018180, 2025). "Interestingly, several adult patients with heterozygous Notch3 stop codon mutations leading to haploinsufficiency have been diagnosed with cerebral small vessel disease." (PMID 38015629, 2024). "NOTCH3 variants are the leading cause of hereditary cerebral small vessel disease (SVD)." (PMID 39191170, 2024). "Pathogenic variants in NOTCH3 are the main cause of hereditary cerebral small vessel disease (SVD)." (PMID 38713890, 2024). "CADASIL is a NOTCH3-associated cerebral small vessel disease." (PMID 31667734, 2020). "Overall, our findings provide support for the temporal sequence of events and the molecular connections that link vascular dysfunction to neuronal degeneration and identify Notch3 as a critical culprit in cerebral small vessel disease that emerges with age." (PMID 38015629, 2024). "Therefore, NOTCH3 cysteine-sparing mutations located in the higher EGFr domains might represent an underrecognized risk factor for cerebral small vessel disease, suggesting the need for increased awareness and investigation into these variants’ impact on the disease’s pathology." (PMID 39201482, 2024). "The present study identified a total of 22 patients with mutations in NOTCH3, HTRA1, and COL4A1, which are known to cause cerebral small vessel disease (SVD)." (PMID 37237429, 2023). "Although our data does not include detailed information on genetic tests for mutations in the NOTCH3 gene, we expected the introduction of a distinct ICD-10 code to minimize overlap with other monogenic cerebral small vessel diseases or phenotypically similar conditions." (PMID 37521283, 2023).
cerebral small vessel disease (continued). "The role of NOTCH3 PV in the general population in relation to cerebral small-vessel disease will probably be clarified in the near future as large study cohorts become available, including not only exome- and genome-sequencing data, but also MRI and other clinical phenotyping." (PMID 30032161, 2019). "In this study, we compared the longitudinal changes in cerebral small vessel disease markers and cognitive function between subcortical vascular mild cognitive impairment (svMCI) patients with and without NOTCH3 variant [NOTCH3(+) svMCI vs. NOTCH3(–) svMCI]." (PMID 33716917, 2021). "Although protein modeling suggests that the exon 9 mutation S497L causes significant changes of NOTCH3 secondary structure, genetic and clinical evidences suggesting association between the exon 9 mutation and cerebral small vessel disease/ischemic stroke are still lacking." (PMID 26270344, 2015). "CADASIL (NOTCH3), CARASIL (HTRA1), 6p25 deletion syndrome, cerebral small-vessel diseases (FOXC1 and PITX2) are the typical entities within this group." (PMID 32849169, 2020). "As a result, CADASIL can now be definitively diagnosed through genetic testing of NOTCH3 or detection of GOM in skin biopsy specimens, consistent with the first guideline on the diagnosis and management of cerebral small vessel diseases recently proposed by the European Academy of Neurology." (PMID 38254727, 2024).
dementia (37 papers, 2009 to 2025). Loss of intellectual abilities interfering with an individual's social and occupational functions. "All patients carrying variants in APP, CSF1R, ITM2B (p.Ile251Val), and NOTCH3 genes showed a family history for dementia." (PMID 33770234, 2021). "Our findings suggest that APOE ε4 can be used as a marker for the development of dementia in elderly CADASIL patients with less pathogenic NOTCH3 variants." (PMID 33328970, 2020). "Conversely, given that nearly 60% of patients with pathogenic NOTCH3 variants reported a positive family history of dementia, family history should be actively elicited during the course of the diagnostic evaluation as its presence increases the index of suspicion of an underlying genetic disorder." (PMID 33597917, 2021). "Evaluation of high- and moderate-impact rare variants in genes that were previously established as genetically or functionally associated with AD or dementia revealed a missense mutation in NOTCH3 (rs149307620; p.A284T) that was present in 10 AD cases, but no controls (eTable 4 in the Supplement)." (PMID 30924900, 2019). "Although mutations in the human Notch 3 gene caused a genetic form of vascular stroke and dementia, its role in arteriovenous malformations development has been unknown." (PMID 25846406, 2015). "Previous studies have demonstrated that clinical expression of NOTCH-3 mutations in the general population is highly variable between individuals and families, ranging from asymptomatic mild small vessel disease to more severe forms of dementia and cerebral vascular disease." (PMID 35833984, 2022). "Another two probands carried the CADASIL hotspot PV NOTCH3 p.R544C and suffered from dementia prior to the ICH event." (PMID 36580209, 2023). "CADASIL was also confirmed in the patient’s mother, whose symptoms were predominantly dementia and cognitive impairment, despite having the same gene sequence (NOTCH3 gene on chromosome 19—locus 19p13.1–p13.2; OMIM: 125310)." (PMID 36902751, 2023). "All dementia cases in NOTCH3 carriers were of vascular origin (and occurred after enrolment into UK Biobank)." (PMID 33712516, 2021). "Thirteen of 63 patients (20.6%) showed conversion to dementia on follow-up: 1/9 (11.1%) among the NOTCH3(+) svMCI group and 12/54 (22.2%) among the NOTCH3(–) svMCI group." (PMID 33716917, 2021). "Our findings with the NOTCH3 and TREM2 variants suggest that mutations in the same gene can result in dissimilar types of dementia." (PMID 30924900, 2019). "NOTCH3 carriers had increased vascular dementia risk (OR, 5.42; 95% CI, 3.11-8.74), HTRA1 carriers an increased all-cause dementia risk (OR, 2.17; 95% CI, 1.28-3.41), and COL4A1/2 carriers an increased intracerebral hemorrhage risk (OR, 3.56; 95% CI, 1.34-7.53)." (PMID 36300346, 2022). "The time to dementia diagnosis was 11 months in one NOTCH3(+) svMCI patient." (PMID 33716917, 2021). "Cox regression model showed that dementia risk was not significantly different between NOTCH3(+) and NOTCH3(–) svMCI patients after controlling for age, sex, education, and PiB positivity (p = 0.763; adjusted hazard ratio, 0.723; 95% confidence interval, 0.088–5.926)." (PMID 33716917, 2021). "When these data is combined with data we have previously published we conclude that among 105 dementia patients, 5.7% are attributable to PSEN1 mutations (6/105), 2.9% (3/105) to C9ORF72 and TREM2 each, and 0.95% (1/105) to MAPT, GRN and NOTCH3 each, while 85.7% (90/105) remain unclear." (PMID 27632209, 2016). "It is caused by mutations in the NOTCH3 gene and results in aggregation of NOTCH3 extracellular domain in granular osmiophilic material (GOM) within blood vessel walls, degeneration of vascular smooth muscle cells (VSMCs) and a small vessel disease (SVD) type dementia." (PMID 25303037, 2015).
dementia (continued). "Among the genes associated with both CMBs and dementia, the NOTCH3 and APOE genes were both found to be involved in AP-2 transcription regulation, suggesting that vitamins, growth factors, and vesicle-mediated transport may contribute to CMBs-associated dementia." (PMID 33352859, 2020). "Thirty-five patients with clinical and neuroimaging features of cerebral SVD and a confirmed NOTCH3 CADASIL and 35 healthy controls age-matched controls without diabetes, vascular disease, dementia or other neurological or psychiatric disease were enrolled in the study." (PMID 35833984, 2022).